TWIST1 (twist family bHLH transcription factor 1)
Diseases named in the same sentence as TWIST1 in open-access papers (continued):
Sharing a sentence is not in itself a finding about the gene and the disease.
tumor (continued). "In addition to regulating vascular growth factors/receptors and activating endothelial cells in existing vessels, Twist1 can also enhance angiogenesis by inducing trans-differentiation of tumor cells into endothelial cells." (PMID 28099910, 2017). "The expression of TWIST1 is also regulated by Hypoxia-inducible factor (HIF)-1α, a protein associated to hypoxic tissue areas and related to proliferation, differentiation, and development of an aggressive tumor phenotype." (PMID 29152120, 2017). "EMT‐TFs, such as TWIST1, are also found to be highly expressed in a subpopulation of cells within a tumor with the highest invasive and metastatic potential at the invading front of the primary tumor, further supporting the importance of EMT in the metastatic cascade." (PMID 28085222, 2017). "According to these results, we proposed that the Twist1 protein level was fine-tuned by two signaling pathways; one was a known oncogenic signaling pathway NF-κB–Twist1, whereas the other was a new identified tumor-suppressing pathway NF-κB–miR186–Twist1." (PMID 28394356, 2017). "A high Twist1 expression level directly suppresses E-cadherin expression by interacting with its promoter, and it promotes the synthesis of N-cadherin and fibronectin, thereby remodeling the phenotype and enhancing cell motility and tumor progression." (PMID 28032603, 2017). "The combination of EGCG and cisplatin markedly down-regulate the expression of NF-κB p65, Bmi-1, Twist1, and vimentin and up-regulates E-cadherin in human nasopharyngeal CNE2-SCs from the tumor nodules of nude mice, which is associated with the inhibition of tumorigenesis." (PMID 28942499, 2017). "The distal-less homeobox gene 4 (DLX4), a member of the DLX family widely expressed in various cancers, has also been shown to bind to regulatory regions of the Twist1 gene and enhances tumor migration, invasion, and metastasis in cell models and tumor tissues." (PMID 28099910, 2017). "Moreover, Twist1 is required for thrombin-induced angiogenesis and thrombin up-regulates Twist1, thus promoting endothelial cell migration, matrigel tubule formation, and tumor angiogenesis." (PMID 28099910, 2017). "The NF-κB pathway is thought to have a role in oncogenic function; however, in our study, we revealed that NF-κB acted as a tumor suppressor by inducing miR186 expression and subsequently downregulating Twist1 expression in BPH1 and P69 under inflammatory stimulation." (PMID 28394356, 2017). "Additionally, extensive studies have demonstrated that Twist1 is also involved in other steps of the tumor invasion and metastasis process such as the formation of invadopodia, intravascular migration, extravasation and vasculogenic mimicry (VM) formation." (PMID 28099910, 2017). "The overexpression of TWIST1 has been reported in previous studies showing that it could be a biomarker for tumor progression and metastasis." (PMID 26683359, 2016). "Mechanistically, Twist1 appears to confer these properties on tumor cell populations through EMT." (PMID 27023622, 2016). "Although Twist1 is known as a master regulator of mesoderm development, it is unknown whether Twist1 could be involved in endothelial transdifferentiation of tumor-derived cells." (PMID 26823670, 2016). "To date, the predominant role of TWIST1 in tumor progression is thought to be inducing EMT." (PMID 27280289, 2016). "Tumor-derived endothelial differentiation is important for Twist1-induced tumor metastasis, and inhibition of the angiogenesis process may be equally important to treat metastasis." (PMID 26823670, 2016). "The identification of downstream activators of Twist1 could provide valuable information about tumor angiogenesis and metastasis." (PMID 26823670, 2016).
tumor (continued). "Twist1 orchestrates a variety of cellular programs in development and tumor progression." (PMID 27105506, 2016). "Moreover, through direct repression of E-cadherin cells and activation of mesenchymal markers, TWIST1 plays an essential role in tumor metastasis." (PMID 26892682, 2016). "Moreover, the inverse relationship between the expression levels of miR186 and Twist1 is confirmed in vivo tumor metastasis experiment and clinical specimens." (PMID 27121312, 2016). "They identified seven miRNAs, miRs-300, -382, -494, -495, -539, -543, and -544, located in this region that serve as tumor suppressors by cooperatively repressing an EMT signaling network comprising TWIST1, BMI1 polycomb ring finger proto-oncogene, ZEB1/2, and the miR-200 family." (PMID 26784241, 2016). "Both Twist1 and Twist2 can promote tumor progression through strong induction of EMT programs." (PMID 27023622, 2016). "Recently, Twist1 has been found to be a vital oncogene that promotes the development and progression of malignant tumor by enhancing tumor-related functions such as epithelial-to-mesenchymal transition (EMT), angiogenesis, degeneration of ECM, and anti-apoptosis." (PMID 27793033, 2016). "Zeb1 and Twist1 transcript expression in the recovered tumor cells was determined by cDNA qPCR." (PMID 27270319, 2016). "In tumor growth and metastasis, however, the interaction between Twist1 and EMT is paramount." (PMID 27023622, 2016). "As a potent inducer of EMT, strictly control of cellular Twist1 levels could prevent tumor cells from acquiring invasive capacities." (PMID 26959880, 2016). "However, continuous Twist1 activation was revealed to inhibit proliferation of disseminated tumor cells at distant sites, whereas transient expression of Twist1 re-enabled colonization and resulted in metastatic outgrowth." (PMID 27105506, 2016). "However, in distant sites, turning off Twist1 is essential to allow disseminated tumor cells to proliferate and form metastases." (PMID 26985909, 2016). "To confirm whether Twist1 controls tumor growth in vivo, we generated xenograft tumors by subcutaneous injection of H1650shTw or H1650 cells." (PMID 26360779, 2015). "Hypermethylation of the tumor stroma may represent an alternative mechanism for regulation of TWIST1." (PMID 25528769, 2015). "Stromal cell staining ranged from minimal to extensive, while only rare TWIST1 expression could be found in tumor cells." (PMID 25528769, 2015). "The results revealed that TWIST1 was highly expressed in the BNHL tumor tissue." (PMID 25289047, 2014). "In addition, the association between TWIST1 expression and BNHL tumor progression was further analyzed." (PMID 25289047, 2014). "They proposed that TWIST1 expression in the tumor could be used as a potentially prognostic indicator." (PMID 25238494, 2014). "Sun reported that Twist1 (an EMT trigger marker) was frequently overexpressed in the nuclear relocation occurring in VM (vasculogenic mimicry)-positive HCCs, and Twist1 nuclear expression in EMT was likewise associated with VM formation, and with the tumor invasion and metastasis of HCC." (PMID 25180681, 2014). "Since Twist1 positively regulates tumor angiogenesis, Twist1-Tie2 signaling may be involved in the mechanisms of tumor-angiogenesis as well, in which vascular permeability is increased." (PMID 24023872, 2013). "Furthermore, suppression of TWIST1 expression in tumor cells can lead to inhibition of metastatic potential." (PMID 23741524, 2013). "TWIST1 plays a key role in EMT-mediated tumor invasion and metastasis." (PMID 23368843, 2013). "Strikingly, the same interplay between H3K4me3 and H3K27me3 occurs for master genes involved in the EMT process, such as PDGFRα, which is essential for Twist1 to promote tumor metastasis via invadopodia, and the splicing regulator ESRP1, which is repressed by Snail1 to promote EMT." (PMID 24367927, 2013).
tumor (continued). "In light of our results, it would be interesting to see whether miR-337 is able to acquire a tumor suppressor function when co-expressed with miR-151 in TWIST1 positive tumors." (PMID 23741524, 2013). "Furthermore, TWIST1 mRNA was highly expressed in tumor stroma and positively related to tumor stromal content (P <0.001)." (PMID 22967435, 2012). "Twist1 is one of essential factors to promote tumor metastasis." (PMID 23133563, 2012). "Interestingly, CT-LSL OFF lung tumors showed tumor stasis by serial microCT over the course of the 4 weeks of Twist1 inactivation in stark contrast to the progressive tumor growth seen for the control LSL OFF tumors (18% versus 220% growth, p<0.0001 t-test)." (PMID 22654667, 2012). "This suggests that tumors with high expression of TWIST1 are more aggressive, a finding that fits with experimental data where overexpression of TWIST1 resulted in increased extravasation during the dissemination of tumor cells." (PMID 22967435, 2012). "Nevertheless, the observation of claudin-low tumors in WAP-Cre;K-RasG12D;Twist1 transgenic mice suggested that the development of these neoplasms could rely upon an EMT-driven process affecting epithelial cells formerly engaged in differentiation." (PMID 22654675, 2012). "In our model TWIST1 expression also favored cell mobility and could therefore enhance the metastatic potential of tumor cells." (PMID 22272264, 2012). "Twist1 has been strongly implicated in tumor progression, but no studies have examined the effect of Twist1 alone for autochthonous tumorigenesis." (PMID 22654667, 2012). "As the prognostic value for TWIST1 mRNA expression is confined to ER-positive breast cancer, we assessed whether ER expression might be of relevance for TWIST1 mRNA expression in tumor tissues with a variable amount of stromal content." (PMID 22967435, 2012). "Twist1 has been suggested to play an important role during tumor progression." (PMID 22654667, 2012). "Indeed, the detailed analysis of the correlation between TWIST1 expression levels and OS and DFS, at each tumor pathological stage, showed an interaction between these two variables, pathological tumor stages and TWIST1 expression." (PMID 21464926, 2011). "Of 151 tumor samples tested, TWIST1 was detected in 130 cases (86.1%)." (PMID 21464926, 2011). "Given their function in HNSCC and other tumor types, Twist1 and Snail expression levels are likely good candidates for monitoring the invasive and metastatic potential of primary HNSCC, and may be useful in predicting patient response to chemotherapy." (PMID 24212639, 2011). "In addition, TWIST1 over-expression has been found in tumor tissues such as rhabdomyosarcoma, melanoma, pediatric osteosarcoma, T-cell lymphoma, gastric, prostate and breast carcinoma." (PMID 21464926, 2011). "Accordingly, over-expression of ZEB2 and TWIST1 in surgical samples of both normal and tumor tissues can induce EMT, resulting in over-expression of representative EMT markers VIM, FN, and COLs and membrane signal transducers IL8, CXCL4, CCL5, CXCR4, PDGFRB, and TLR2." (PMID 21533028, 2011). "This work gives the first insights regarding the TWIST1 gene in Felis catus, so in the future, we may contribute to the study of the molecular mechanisms affecting its expression profile in cat tumor cells." (PMID 21037858, 2010). "Understanding the molecular mechanisms regulating the TWIST1 gene expression profiles in tumor cells may give new insights regarding prognostic factors and novel therapeutic targets in veterinary oncology." (PMID 21037858, 2010). "Furthermore, SOX11 was found to promote HNSCC tumor growth and the expression of TWIST1 in vivo." (PMID 41511366, 2026). "Primary cortical neurons co-cultured with 4T1 cell tumor-derived EVs displayed dendritic atrophy phenotype, characterized by reduced dendrite complexity and decreased branch number and dendritic length, an effect rescued by knockdown of Twist1 in stable 4T1 cells." (PMID 40963917, 2025).
tumor (continued). "Although whether subcutaneous inoculation of 4T1 cells induces brain metastasis remains unclear, circulating tumor cells may reach the mPFC, change the local microenvironment, and upregulate Twist1 expression to induce neuronal dendritic atrophy in tumor-bearing mice." (PMID 40963917, 2025). "Next, we aimed to identify whether tumor cells-derived Twist1 is essential for CID." (PMID 40963917, 2025). "Therefore, we investigated whether tumor cell-derived EVs-encapsulated Twist1 regulates dendritic morphogenesis in vivo." (PMID 40963917, 2025). "Likewise, more twist-related protein 1 (TWIST1) can be found in the metastatic tumor cells." (PMID 38252369, 2024). "To test this hypothesis, we performed experimental therapy combining Twist1 inhibition with CAR T cell infusion, in which a fully murine system we recently developed was used to specifically target tumor cells expressing mouse Egfrviii, a hallmark of GBM-associated mutation." (PMID 38416830, 2024). "The difference in TWIST1 expression may be due to tumor heterogeneity." (PMID 38229014, 2024). "At the molecular level, EMT transcription factors, including Snail, ZEB1, and Twist1, attract immunosuppressive cells through the production of chemokines or promote the expression of immunosuppressive checkpoint molecules, thus forming a tumor immunosuppressive microenvironment." (PMID 37926835, 2023). "Finally, Twist1 expression promotes vascularization in tumor xenograft models." (PMID 37208442, 2023). "Consequently, the number of sgTWIST1 cells recovered from primary neurospheres was statistically significantly lower compared to Control cells, indicating the role played by TWIST1 in propagating a highly tumorigenic subpopulation of NB cells enriched in tumor-initiating cells (TIC)." (PMID 35022561, 2022). "Additionally, the expression of TWIST1, SNAI1, FN1, and CDH2 also showed significant association with NUTF2, suggesting that NUTF2 may play a major tumor-promoting role in the Lumina A BRCA subtype." (PMID 35155261, 2022). "Finally, after crossing the TWIST1-tumor-stroma signature with the secretome of cells, we could identify 17 commonly DE terms, among which 14 were also found to be in common with the transcriptome of cells." (PMID 35022561, 2022). "Previous results reported by researchers associate with this study found that Twist1 production depends on TP-induced reprogramming of tumor metabolism to promote HCC cell VM formation and metastasis by invoking the pentose Warburg effect, thereby promoting tumor development." (PMID 36059624, 2022). "However, the mechanisms by which TWIST1 affect the metastasis of tumor cells remains unclear, although mechanisms are believed to differ depending on tumor type." (PMID 35052775, 2022). "Although recent study has demonstrated that MYBL1 promotes growth and metastasis of HCC cells via upregulated TWIST1 expression, however, the clinical significance and molecular mechanisms of MYBL1 underlying tumor angiogenesis in HCC remain remains largely unknown." (PMID 35987690, 2022). "However, TWIST1 has known roles in the carcinogenesis of tumor cells." (PMID 35052775, 2022). "In addition, to confirm that HK2 can regulate EMT in CRC, we performed IHC staining to detect TJP1, E‐cadherin, vimentin and Twist1 expression in the tumour tissues of CRC patient samples, and the immunohistochemical staining of these proteins exhibited different degrees of positivity." (PMID 34378321, 2021). "Twist1 overexpression can induce tumor cell metastasis, whereas Twist2 is involved in the tumor growth stage; these two proteins have different functions in different tumor types The bHLH domain can specifically bind to the E-box domain on DNA to play a regulatory role." (PMID 33397409, 2021). "In addition, it has been reported that TWIST1 could transcriptionally regulate VE-cadherin, a transmembrane protein responsible for cell–cell adhesion and VM formation, in multiple types of tumor cells." (PMID 33510354, 2021).
tumor (continued). "This study suggests that the pro-tumor effects of TWIST1 might mainly come from the tumor stroma." (PMID 34768901, 2021). "In tumor cells, Twist1 and Snail1 could repress E-Cadherin and upregulate mesenchymal genes." (PMID 31931858, 2020). "Moreover, we demonstrated that two of the four upregulated genes (AMAM22 and TWIST1) were positively correlated with tumor stage in two independent cohorts, and KLHL13 was upregulated in subjects lacking of telomere maintenance, indicating the clinical relevance of the UHR-NB upregulated genes." (PMID 32629858, 2020). "Hence, MYC and TWIST1 overexpression in cancer may be eliciting tumor invasion by activating embryonic programs that otherwise physiologically enable mesodermal migration." (PMID 31933479, 2020). "Thus, we found that the B domain (bHLH domain) of SPZ1 may be critical for tumor growth, invasion, and metastasis in vivo, possibly through interaction with TWIST1." (PMID 30154425, 2019). "Twist1 is a pivotal regulator of EMT and reported to promote N-cadherin synthesis and inhibit E-cadherin expression, thus causing profound morphological changes in tumor cells and expression of cell-matrix adhesion genes to induce tumor cell mobility and migration." (PMID 30021598, 2018). "Moreover, the cross-talk between Twist1 and tumor angiogenesis has also attracted great attention." (PMID 28099910, 2017). "Stromal cells may influence tumor budding in CRCs through expression of TWIST1." (PMID 29258163, 2017). "However, TWIST1 has also been involved in pathological processes such as tumor metastasis." (PMID 29165393, 2017). "In addition to secreting soluble factors, Twist1 may enhance the tumor-promoting ability of CAF by augmenting ECM-remodeling because ECM greatly influences on the behavior of cancer cells." (PMID 29029429, 2017). "Additionally, the formation of the Bcl-2/Twist1 complex is stimulated when tumor cells are hypoxic." (PMID 28032603, 2017). "Neither tumor location nor metastasis stage was associated with TWIST1 or TWIST2 expressions." (PMID 29156759, 2017). "Therefore, MACC1 as a transcriptional factor could transcriptionally modulate endothelium-dependent angiogenesis and mediate TWIST1 upregulation, which is responsible for the angiogenesis and tumor progression of GC." (PMID 27280289, 2016). "Other reports identified that Twist1 expression could enhance the tumor response to radiotherapy." (PMID 27835599, 2016). "Finally, we have shown that Twist1 downregulation inhibits tumor growth in a nude mouse xenograft model, suggesting that the inhibition of Twist1 may be a potential therapeutic target." (PMID 26360779, 2015). "Among them, EGFR(7p11.2), TWIST1(7p21.2), RAC1(7p22), MTDH(8q22.1), CCNE2(8q22.1), TNFRSF11B(8q24) and GRB2(17q25) might be good candidates, as they are reportedly associated with invasiveness and metastasis of tumor cells." (PMID 23457519, 2013). "Thus, Twist1 may act both to induce malignancies early in tumorigenesis and also promote tumor progression." (PMID 22654667, 2012). "Additionally, tumor tissues showing weak/moderate TWIST1 protein staining were mostly ER-negative." (PMID 22967435, 2012). "As evidenced by the significant increase in the expression of both Twist1 and Sox2 in the necrotic tumor areas, and their co-regulatory effect in siRNA transfectants, we next asked whether this expression is the co-regulatory mechanism necessitated by the interaction between Twist1 and Sox2." (PMID 22184289, 2011). "TWIST1 expression was restricted to tumor tissues, indicating that it could be a tumor marker." (PMID 21464926, 2011). "Expression of TWIST1 by tumor cells might enhance the intravasation steps of metastasis." (PMID 21464926, 2011).